TOP1MT (DNA topoisomerase I mitochondrial)
Diseases named in the same sentence as TOP1MT in open-access papers:
TOP1MT is named in the same sentence as 25 diseases in open-access papers, as found by Europe PMC text mining. Sharing a sentence is not in itself a finding about the gene and the disease. The quoted sentences say what the papers report.
breast carcinoma (3 papers, 2017 to 2019). "A combination of an AKT inhibitor and a TOP1MT inhibitor therefore can be proposed to treat non-TNBC, but not necessarily for TNBC breast cancers." (PMID 31107860, 2019).
colon carcinoma (2 papers, 2019 to 2021). "To study the function of TOP1MT in tumor development, we transplanted TOP1MT-deficient and TOP1MT-proficient HCT116 colon carcinoma cells generated by CRISPR/Cas9 into the flank of female nude mice." (PMID 30622257, 2019). "Based on the marked overexpression of TOP1MT in colon tumors, we utilized HCT116 colon carcinoma cells as a model system, as this cell line shows the highest TOP1MT expression among the NCI-60 colon cancer cell lines." (PMID 30622257, 2019).
gastric cancer (2 papers, 2017 to 2024). A primary or metastatic malignant neoplasm involving the stomach. "Here, we examined the role of TOP1MT in gastric cancer (GC) and attempted to determine the underlying mechanism." (PMID 28874393, 2017). "This study demonstrates the crucial role of TOP1MT in promoting gastric cancer progression by regulating aerobic glycolysis." (PMID 38200513, 2024). "Moreover, the correlations between TOP1MT and pathway score was analyzed with Spearman, and results showed that TOP1MT was negatively correlated with glycolysis and gluconeogenesis in gastric cancer." (PMID 38200513, 2024). "In conclusion, this report primarily examined the role of TOP1MT in gastric cancer." (PMID 38200513, 2024). "Therefore, in conjunction with our ongoing research, TOP1MT has the potential to play a crucial role in regulating tumor metabolism and could contribute to the development of novel treatment strategies for gastric cancer." (PMID 38200513, 2024). "Our previous studies have found that TOP1MT is a crucial gene that inhibits glycolysis and cell metastasis of gastric cancer (GC) cells, but the mechanism of its regulation of glycolysis remains unclear." (PMID 38200513, 2024).
head and neck squamous cell carcinoma (2 papers, 2022 to 2023). A squamous cell carcinoma that arises from any of the following anatomic sites: lip and oral cavity, nasal cavity, paranasal sinuses, pharynx, larynx, and salivary glands. "CREB5 inhibits mitochondrial apoptosis by promoting the transcription of TOP1MT in head and neck squamous cell carcinoma." (PMID 37821801, 2023).
liver cancer (2 papers, 2019 to 2022). An epithelial or non-epithelial malignant neoplasm that arises from the liver. "TOP1MT ribosome functions are linked to the biological function of TOP1MT in patients with liver cancer." (PMID 36035140, 2022). "Here, we report that TOP1MT is overexpressed in cancer tissues and demonstrate that TOP1MT deficiency attenuates tumor growth in human and mouse models of colon and liver cancer." (PMID 30622257, 2019). "TOP1MT maintains tumor cell proliferation and promotes tumor growth in mice models of colon and liver cancers with impaired metabolism." (PMID 36035140, 2022). "The TOP1MT genomic signature profile, based on Top1mt-KO liver cancers, is correlated with enhanced survival of hepatocellular carcinoma patients." (PMID 30622257, 2019).
delirium (1 paper, 2025). A disorder characterized by confusion; inattentiveness; disorientation; illusions; hallucinations; agitation; and in some instances autonomic nervous system overactivity. "There were eight protective genes (DHODH,DHRS7B,TOP1MT,CASP8,GFM1,CPT1B,TK2,GPD2), and four genes (SCP2,DMPK,GSTK1,SIRT3) that increased delirium risk, as shown inFigure 2, withp = 0.05 (dotted line); and false discovery rate (FDR) < 0.05 (red asterisks)." (PMID 41330563, 2025). "Our findings show that higher expression of 8 genes, includingDHODH,DHRS7B,TOP1MT,CASP8,GFM1,CPT1B,TK2, andGPD2, could decrease the risk of delirium." (PMID 41330563, 2025).
diabetes (1 paper, 2024). "The expression of mitochondrial transcription genes such as Twinkle, top1mt, and SSDBP1 were reduced in hypertrophy and heart failure due to diabetes, which further caused reduced mitochondrial biogenesis, while exercise training increased the expression level of mitochondrial transcription genes." (PMID 39795867, 2024).
Hepatic (1 paper, 2019). "Hepatic tumor burden was significantly decreased in Top1mt-KO mice as compared to the WT littermates at 50 weeks after DEN injection (p = 0.04, t-test)." (PMID 30622257, 2019).
Hepatic fibrosis (1 paper, 2019). The presence of excessive fibrous connective tissue in the liver. "We found no obvious differences in the extent of hepatic fibrosis between WT and Top1mt-KO mice." (PMID 30622257, 2019).
hepatocellular carcinoma (1 paper, 2019). A malignant tumor that arises from hepatocytes. "Here, the authors show that TOP1MT has a tumor promoting role in hepatocellular carcinoma by supporting mitochondrial translation and that its deficiency limits tumorigenicity." (PMID 30622257, 2019). "As TOP1MT is strongly upregulated in a wide range of cancers, including colon and liver carcinomas, we investigated the impact of TOP1MT on carcinogenesis." (PMID 30622257, 2019).
hyperlipidemia (1 paper, 2024). "High fat diet with 40% calories coming from fat (mainly lard) was used in this study, which induced liver weight gain as expected, and Top1MT KO mice fed for 16 weeks with high fat diet developed hyperlipidemia and hypertransaminasemia." (PMID 39372760, 2024).
liver steatosis (1 paper, 2024). "We show that after 16 weeks of HF diet, mice lacking Top1MT are prone to the development of severe MASH characterized by liver steatosis, lobular inflammation and hepatocyte damage." (PMID 39372760, 2024).
lung carcinoma (1 paper, 2017). "Further studies are warranted to determine the potential linkage of the two SNP variants (V256I and R525W) in lung cancers and melanomas and to determine the possible relevance of TOP1MT mutations as a source of mitochondrial diseases and susceptibility to therapies." (PMID 28819183, 2017). "Yet, it is also noteworthy that in these same homozygous V256I lung cancer cell lines, expression of the TOP1MT gene is suppressed." (PMID 28819183, 2017).
prostate carcinoma (1 paper, 2019). A carcinoma that arises from epithelial cells of the prostate gland. "On the other hand, the only cell line that showed negative coefficients for TOP1MT was LNCAP (prostate cancer), which turned out to be the cell line that has the smallest average CSS scores for drug combinations involving the TOP1MT inhibitor (topotecan)." (PMID 31107860, 2019).
scleroderma (1 paper, 2025). Scleroderma is a rare autoimmune connective tissue disorder characterized by abnormal hardening of the skin and, sometimes, other organs. "P2 and P4 sera were obtained from patients with scleroderma withknown anti-topoisomerase I antibodies.42−46 MS analysis of the P2 serum immunoprecipitate showedthe presence of both cytoplasmic topoisomerase I (TOP1) and mitochondrialtopoisomerase 1 (TOP1MT), two highly homologous proteins." (PMID 39814365, 2025).
spinocerebellar ataxia (1 paper, 2022). "Here, we identify a novel spinocerebellar ataxia variant, occurring in a patient with mutations in both ataxin-7 and top1mt." (PMID 35422034, 2022). "In summary, we show that concurrent mutations within ATXN7 and TOP1MT are associated with a novel spinocerebellar ataxia variant." (PMID 35422034, 2022). "Here, we present a novel spinocerebellar ataxia variant occurring in a patient with mutations in both ATXN7 and TOP1MT, which encodes mitochondrial topoisomerase I (top1mt)." (PMID 35422034, 2022). "Our work provides important insight into the cellular biology of ataxin-7 and top1mt and offers insight into the pathogenesis of spinocerebellar ataxia applicable to multiple subtypes of the illness." (PMID 35422034, 2022).
steatosis (1 paper, 2024). Increased lipid within the cytoplasm of cells. "Histopathological analysis assessed by Oil Red O staining established pronounced steatosis in Top1MT KO mice with elevated lipid accumulation." (PMID 39372760, 2024). "In addition, high fat diet-fed Top1MT KO mice manifested a histological liver phenotype of MASH: lipid deposition (steatosis), local ballooning and liver damage (Figure." (PMID 39372760, 2024).
tumor (10 papers, 2017 to 2025). "In order to further verify the role of TOP1MT in GC, we analyzed the clinical data of 295 patients with GC and found that TOP1MT deficiency was related to the increased tumor metastasis or recurrence and shorter survival time." (PMID 28874393, 2017). "Mechanistically, we show that TOP1MT associates with mitoribosomal subunits, ensuring optimal mitochondrial translation and assembly of oxidative phosphorylation complexes that are critical for sustaining tumor growth." (PMID 30622257, 2019). "This indicated that TOP1MT deficiency promoted the invasion and metastasis of tumor cells mainly through the Warburg effect and that LDHA may have played an important role in this process." (PMID 28874393, 2017). "Thus, we conclude that mitochondrial dysfunction caused by the loss of TOP1MT induces oxidative stress, reduces energy supply and impairs the anabolic function of mitochondria limiting building blocks, ultimately resulting in suppressed tumor growth." (PMID 30622257, 2019). "Therefore, our present study results indicated that TOP1MT may be an underlying target gene regulating tumor metabolism, potentially contributing to the development of novel therapeutic strategies in clinical oncology." (PMID 28874393, 2017). "Four clinical variables were applied in the WGCNA: TOP1MT Expression (high or low), sex, events, and tumor grade." (PMID 38200513, 2024). "TOP1MT regulates tumor development and is a potential biomarker for targeted mitochondrial anticancer therapy." (PMID 36035140, 2022). "It is noteworthy that the mRNA expressions of TOP2A and TOP1MT were upregulated progressively with advancing stage in many tumor types." (PMID 36288358, 2022). "Lower TOP1MT expression was discovered in tumor samples from KICH, THCA, and OV than in normal tissues." (PMID 36035140, 2022). "First, we found that both CREB5 and TOP1MT were significantly higher in tumor tissues than in the normal control." (PMID 35773668, 2022). "Cholesterol-modified siCREB5 and siTOP1MT were used to silence the expression of CREB5 and TOP1MT in the xenograft tumor models." (PMID 35773668, 2022). "Low TOP1MT expression was discovered in tumor samples from KICH, THCA, and OV than that in normal tissues." (PMID 36035140, 2022). "For example, TOP1MT on 8q24.3, a mitochondrial DNA topoisomerase, was the gene with the most significant difference in expression by race in both tumor types." (PMID 32819446, 2020). "Our results reveal the importance of TOP1MT for tumor development and identify TOP1MT as a potential target for anticancer therapies." (PMID 30622257, 2019). "Overall, these findings demonstrate the role of TOP1MT in promoting tumor growth and support the prognostic value of the TOP1MT genomic signature for HCC patients." (PMID 30622257, 2019). "To elucidate how TOP1MT affects mitochondria in tumor cells, we analyzed the TOP1MT-KO and WT xenograft tumors by electron microscopy." (PMID 30622257, 2019). "Increased TOP1MT copies (gain and amplification) in tumor tissues significantly increased TOP1MT mRNA expression unlike copy neutral (diploid) and copy loss (shallow deletion)." (PMID 36035140, 2022). "Since tumor cells highly depend on mitochondrial biology and TOP1MT could be a target of cancer drugs, inhibiting TOP1MT could be an effective approach for eliminating cancer cells." (PMID 36035140, 2022). "Notably, in spite of decreased mtDNA, mitochondrial transcript levels were increased in TOP1MT-KO tumor cells per mtDNA molecule, which is consistent with our recent findings in Top1mt-KO MEFs31." (PMID 30622257, 2019). "We discovered that TOP1MT deficiency promoted GC cell invasion and migration; increased glucose consumption, lactate production and LDHA activity in vitro and in vivo and promoted tumor metastasis in patients with GC." (PMID 28874393, 2017).
tumor (continued). "In contrast, the upregulation of TOP1MT in tumor cells may downregulate the Warburg effect, shifting glucose metabolism from glycolysis to oxidative metabolism." (PMID 28874393, 2017). "Indeed, TOP1MT has been shown to be critical for tumor development." (PMID 31226795, 2019). "Therefore, Inhibitors targeting TOP1MT could be a viable strategy to target mitochondrial DNA due to their involvement in mitochondrial protein synthesis and their heightened expression in different tumor types." (PMID 38200513, 2024). "Treatments demethylating the POLG, TOP1MT, and TFAM genes attempt to increase tumor cell mtDNA copy number, differentiation, and apoptosis." (PMID 37332990, 2023). "Global demethylation of the HSR-GBM1 nuclear genome modified tumor-specific genes and critical mtDNA transcription and replication factors beyond POLG and TOP1MT." (PMID 37332990, 2023). "Linkedomics database was used to analyze the methylation level and copy number changes of TOP1MT in BLCA, HNSC, KIRP, PAAD, UCEC, and LIHC tumor tissues to understand the mechanism of the TOP1MT gene during tumorigenesis." (PMID 36035140, 2022). "Here, we demonstrate that lack of TOP1MT results in delayed and decreased tumor growth due to impaired mitochondrial translation." (PMID 30622257, 2019).
cancer (9 papers, 2013 to 2024). A tumor composed of atypical neoplastic, often pleomorphic cells that invade other tissues. "The results demonstrate a heterologous TOP1MT expression in various cancers; besides, upregulated TOP1MT expression is associated with poor prognosis." (PMID 36035140, 2022). "We identified a new mechanism underlying TOP1MT-deficient GC metastasis and showed that TOP1MT played an important role in cancer cells." (PMID 28874393, 2017). "Interestingly, several variants of Top1mt with altered activity are overrepresented in cancer patients, but it remains to be elucidated at which stage of cancer development these variants might be influential." (PMID 31027213, 2019). "We identified the six most significant cancers by combining the expression features of TOP1MT mRNA in pan-cancerous tissues and prognostic analysis of OS, DSS, and PFI." (PMID 36035140, 2022). "According to Kaplan-Meier survival curve analysis, high TOP1MT expression in BLCA, HNSC, KIRP, PAAD, UCEC, and LIHC cancer tissues was linked to poor prognosis of cancer patients, i.e., poor OS, disease-specific survival, and PFI." (PMID 36035140, 2022). "We found that TOP1MT expression is linked to immune invasion and checkpoint markers in BlCA, HNSC, KIPP, PAAD, UCEC, and LIHC cancers." (PMID 36035140, 2022). "To examine the molecular mechanism underpinning the mitochondrial dysfunction of TOP1MT-KO cancer cells, and because TOP1MT is known to act primarily as a DNA processing enzyme, we examined mtDNA copy number and transcripts." (PMID 30622257, 2019). "On the other hand, elevated mtDNA copy number increases the risk of cancer formation, potentially by satisfying the intensive metabolic demands of proliferating cancer cells, and many cancers do exhibit overexpression of Top1mt." (PMID 31027213, 2019). "Conversely, high TOP1MT expression levels are commonly observed in aggressive cancers (as observed in HCCs)." (PMID 30622257, 2019). "The disease-free survival rates of patients with stage I-III cancer and the overall survival rates of patients with stage IV cancer were shorter in patients with low TOP1MT expression than those in patients with high TOP1MT expression." (PMID 28874393, 2017). "Physiological upregulation of TOP1MT has been observed in cellular stress responses encompassing the induction of mitochondrial biogenesis and in cancer cells, where TOP1MT is induced by the proto-oncogene MYC." (PMID 23982517, 2013). "Furthermore, our findings demonstrate the substantial role of TOP1MT in the functioning of cancer cells." (PMID 38200513, 2024). "Thus, TOP1MT is a potential biomarker for mitochondrial anticancer therapy and cancer immunotherapy." (PMID 36035140, 2022). "This study aims to explore TOP1MT expression in pan-cancer tissues and identify whether it can be a target for mitochondrial anticancer therapy." (PMID 36035140, 2022). "This work examined TOP1MT expression in pan-cancer datasets." (PMID 36035140, 2022). "Furthermore, while we found that the biological functions of TOP1MT of 122 co-expressed genes in six cancer tissues were related to ribosomal functions, limitations were noted." (PMID 36035140, 2022). "Notably, mitochondrial mRNAs are overexpressed in TOP1MT-KO cancer cells, which is in line with our recent genomic analyses of mitochondrial transcription." (PMID 30622257, 2019). "For the first time, we assessed the expression and role of TOP1MT in cancer cells." (PMID 28874393, 2017). "Interestingly, TOP1MT is involved in mitochondrial OXPHOS not only in normal cells but also in cancer cells." (PMID 28874393, 2017). "This means that TOP1MT could play different roles in different cancer types." (PMID 36035140, 2022). "Thus, we anticipate that TOP1MT could be a potential target for intervention in combinational therapies against K-Ras mutant tumors, as well as in cancers with upregulated TOP1MT or high reliance on mitochondrial biogenesis." (PMID 30622257, 2019).
cancer (continued). "This is probably the reason for alterations of Top1mt expression in cancer development, although it appears to depend on the type of cancer whether it is downregulation or enhanced expression of Top1mt that supports cancer development and metastasis." (PMID 31027213, 2019). "Thus, it appears that, depending on the stage, both decreased and increased activity of Top1mt might promote cancer progression and survival." (PMID 31027213, 2019). "Since TOP1MT is vital for the expression of the OXPHOS-related genes in mitochondrial DNA, we hypothesize that TOP1MT deficiency may switch cellular glucose metabolism from OXPHOS to glycolysis because of the impaired OXPHOS in cancer cells." (PMID 28874393, 2017). "The TCGA database was used to evaluate TOP1MT expression in patients with stage I, II, III, and IV cancers, as well as grades G1, G2, G3, and G4." (PMID 36035140, 2022). "Survival analysis showed that the CNVs of TOP2B in 13 cancer types, TOP3B in 7 cancer types, TOP2A in 6 cancer types, TOP1MT in 6 cancer types, TOP3A in 5 cancer types and TOP1 in 5 cancer types significantly correlated with overall prognosis." (PMID 36288358, 2022). "The study’s findings indicate that the absence of TOP1MT plays a role in the proliferation of cancer cells, particularly through the Warburg effect." (PMID 38200513, 2024). "Nonetheless, we did not conduct a pan-cancer analysis on the function of TOP1MT in different cancers." (PMID 36035140, 2022). "First, we searched the database for phenotypic features of TOP1MT expression in various cancers, yet no additional evidence was discovered in the cell, animal, or clinical samples." (PMID 36035140, 2022). "Thus, reduced mtDNA expansion might at least partially account for the observed decrease in cancer cell proliferation in the absence of TOP1MT." (PMID 30622257, 2019). "However, the role of TOP1MT in cancer cells has not been reported." (PMID 28874393, 2017).
TOP1MT also shares sentences with these, for which no sentence is quoted: childhood asthma (1 paper); heart failure (1); melanoma (1); metabolic dysfunction-associated steatohepatitis (1); mitochondrial disease (1); retinoblastoma (1).